ENSG00000212161
Synonyms: LOC124900450
Gene: Small nucleolar RNA gene on chromosome 1 (159,851,906 to 159,851,972, reverse strand). Ensembl gene ENSG00000212161.
Gene Ontology:
Biological process: RNA processing
Cellular component: nucleolus
Homologues: Paralogues in human: SNORD64 (90% identical).